LRRC8A (leucine rich repeat containing 8 VRAC subunit A)
Diseases named in the same sentence as LRRC8A in open-access papers (continued):
Sharing a sentence is not in itself a finding about the gene and the disease.
tumor (continued). "The transcripts per million expression level of LRRC8A in PAAD samples was seven folds higher than that in normal samples (46.52 in tumor samples vs. 6.59 in normal samples)." (PMID 36428619, 2022). "These research directions are poised to investigate the potential role of LRRC8A in tumor heterogeneity, which may contribute to our understanding of precision oncology frameworks." (PMID 41439137, 2026). "However, LRRC8A-deficient MC38 cells showed normal proliferation in vitro, and tumor growth was unaltered." (PMID 41419196, 2025). "We transplanted WT and LRRC8A-deficient MC38 cells into recipient mice and monitored tumor growth." (PMID 41419196, 2025). "The levels of LRRC8A transcripts discovered in different tumours and the difference in LRRC8A expression between normal and tumours tissue lack justification for the impact of genes on survival, suggesting that aspects beyond gene expression need to be studied." (PMID 38909013, 2024). "Aside from the signaling pathways that may affect T-cell function through LRRC8A, factors within the tumor microenvironment (TME) can hinder ion channel function." (PMID 39113714, 2024). "Gene modifications of LRRC8A were examined across various tumour types." (PMID 38909013, 2024). "However, the mechanisms of LRRC8A upregulation as well as the pathways involved in its tumor-promoting role were unexplored." (PMID 36632452, 2023). "Considering the high structural conservation of LRRC8A and the similarity of pro-apoptotic mechanisms between anti-tumour drugs and CDT, it is plausible to postulate that the function of LRRC8A might also be involved in CDT-induced apoptosis in NPTr cells." (PMID 38018865, 2023). "Depletion of NSUN2 significantly inhibited cell growth and metastasis, whereas ectopic expression of LRRC8A in NSUN2-depleted cells could largely rescue the tumor-suppressive effect of NSUN2 knockdown." (PMID 36632452, 2023). "Moreover, LRRC8A is essential for T cell development, and it has been recently reported to play an integral role in tumor immunotherapy." (PMID 36428619, 2022). "Recent studies also supported the finding that LRRC8D and LRRC8A/LRRC8E play an integral role in the regulation of multidrug resistance and tumor immunotherapy, respectively." (PMID 36428619, 2022). "Second, the tumor microenvironment, particularly the extracellular osmolarity and pH, directly influences VRAC activation patterns, which may affect the role of LRRC8A in drug resistance." (PMID 41439137, 2026). "Similar to MC38 cells, Lrrc8a disruption neither affected their proliferation in vitro, nor tumor growth in vivo." (PMID 41419196, 2025). "Activation of tumor-infiltrating T cells was unchanged as surface expression of the activation marker CD44 was not affected by MC38-expressed LRRC8A." (PMID 41419196, 2025). "Our primary aim of this study is to elucidate the potential involvement of KCa3.1 and LRRC8A in regulating CCL2 expression and production through these signaling axes in M2-MACs, as well as their role in CCL2 upregulation under high-[K+]e conditions that mimic the tumor microenvironment." (PMID 40806751, 2025). "Importantly, both KCa3.1 activation and LRRC8A inhibition significantly attenuated high [K+]e-induced CCL2 upregulation, further supporting their regulatory roles under tumor-like ionic conditions." (PMID 40806751, 2025). "This complex interaction may not play a significant role in the reduced tumor growth observed in LRRC8A-KO cells." (PMID 38909013, 2024). "Consistent with a comprehensive in vitro study, Lrrc8a disruption neither affected the proliferation of MC38 or B16-F10 cells in vitro, nor tumor growth in vivo." (PMID 41419196, 2025). "Effects of CD11cCre-driven Lrrc8a disruption were neither observed on MC38 tumor growth, nor on tumor-infiltrating immune cell populations." (PMID 41419196, 2025).
infection (3 papers, 2022 to 2024). The state of being infected such as from the introduction of a foreign agent such as serum, vaccine, antigenic substance or organism. "In line with the results from our screen, infection of HEK293 cells with increasing MOIs of HSV-1 led to reduced protein levels of the VRAC subunit LRRC8A." (PMID 38652659, 2024).
metabolic disease (3 papers, 2022 to 2026). A congenital disorder (due to inherited enzyme abnormality) or acquired (due to failure of a metabolically important organ) disorder resulting from an abnormal metabolic process. "A comprehensive investigation of the metabolic functions of LRRC8A will advance the understanding of and therapeutic approaches to metabolic disorders." (PMID 41439137, 2026). "Through these systems-level research approaches, we may better understand the potential role of LRRC8A in energy metabolism and metabolic diseases, which may contribute to the development of new frameworks for precision metabolic medicine." (PMID 41439137, 2026).
neurological disease (1 paper, 2026). "Multiple studies have validated the links between LRRC8A dysregulation and neurological disorders, metabolic ailments, and tumors." (PMID 41439137, 2026). "Despite significant advances in our understanding of LRRC8A's role in neurological disorders, several substantial limitations persist in the current research." (PMID 41439137, 2026).
LRRC8A also shares sentences with these, for which no sentence is quoted: Obesity (9 papers); diabetes (5); cardiac hypertrophy (2); Hyperglycemia (2); Impaired glucose tolerance (2); liver cancer (2); myocardial infarction (2); adenocarcinoma (1); age (1); atherosclerosis (1); atrial fibrillation (1); brain infarct (1); brain injury (1); clear cell renal cell carcinoma (1); colon adenocarcinoma (1); esophageal cancer (1); esophageal squamous cell carcinoma (1); experimental autoimmune encephalomyelitis (1); glaucoma (1); Head-Neck Squamous Cell Carcinoma (1); hearing loss (1); Hepatic steatosis (1); infectious disease (1); influenza (1); insulinoma (1); kidney injury (1); lipid metabolism disorders (1); liver disease (1); lung adenocarcinoma (1); Lymphadenopathy (1).
A further 9 diseases each share a sentence with LRRC8A in 1 paper.